MYCN (MYCN proto-oncogene, bHLH transcription factor)
Diseases named in the same sentence as MYCN in open-access papers (continued):
Sharing a sentence is not in itself a finding about the gene and the disease.
neuroblastoma (continued). "This study presents ddPCR as an accurate tool to assess MYCN and ALK copy numbers in neuroblastoma cell lines, tumor samples and tumor-derived cfDNA in blood plasma." (PMID 29156716, 2017). "Thirty percent of neuroblastomas have MYCN-amplification featuring elevated N-MYC expression, while the C-MYC is predominantly expressed in MYCN-single copy neuroblastomas." (PMID 29207623, 2017). "We first validated that ML327 represses MYC signaling by demonstrating repression of N-MYC protein expression in the treatment of 4 MYCN-amplified neuroblastoma cell lines and C-MYC repression in 3 MYCN-single copy cell lines." (PMID 29207623, 2017). "Amplification of the MYCN oncogene, a member of the MYC family of transcriptional regulators, is one of the most powerful prognostic markers identified for poor outcome in neuroblastoma, the most common extracranial solid cancer in childhood." (PMID 27448979, 2016). "First, we observed a strong correlation between MYCN and PRMT1 protein levels in primary neuroblastoma tumors." (PMID 27571165, 2016). "A stringent test of whether MYCN destabilization is a viable therapeutic strategy for MYCN-driven cancers is to establish whether murine tumors genetically-engineered to overexpress MYCN, together with primary human neuroblastoma tissue amplified for MYCN, are targeted in vivo." (PMID 27438153, 2016). "To establish the MYCN dependency of both the native neuroblastoma cell line Kelly and the SHEP WT and SHEP T58/S62 mutant MYCN lines, we abrogated MYCN expression via siRNA-mediated knockdown." (PMID 27438153, 2016). "Down-regulation of MYCN, ID2, TERT and FN1 has been also reported in neuroblastoma cells undergoing differentiation upon exposure to retinoids." (PMID 26893368, 2016). "The gene protein arginine methyltransferase 1 (PRMT1) was identified as a MYCN direct target gene and high levels of PRMT1 mRNA correlated with poor prognosis in a series of 88 primary neuroblastoma tumors." (PMID 27571165, 2016). "To test the ability of the GRD domain to rescue tumor suppression in neuroblastoma, we bred the nf1a-/-;nf1b+/+;dbh:wt-GRD;dbh:mCherry transgenic line with the nf1a-/-;nf1b+/+;MYCN;EGFP fish." (PMID 27130733, 2016). "Using miRNAs targeted against MYCN mRNA, Buechner and colleagues noted reduced endogenous N-MYC expression and significantly impaired proliferation in MYCN-amplified neuroblastoma cell lines." (PMID 26771642, 2016). "Here, we analyzed the relationship between MYCN amplification (MNA) status and neuroblastoma prognosis." (PMID 27513929, 2016). "Moreover, we investigated the interplay between MYCN transcriptional and microRNA post-transcriptional regulations and identified several microRNAs, such as miR-124-3p and miR-93-5p, which may significantly contribute to neuroblastoma pathogenesis." (PMID 27167114, 2016). "Thus, the overexpression of MYCN blocks the differentiation of sympathoadrenal precursor cells, leaving them vulnerable to the potentiating effects of nf1 loss on RAS pathway activation, which in turn leads to the marked increased in neuroblastoma penetrance and growth rate." (PMID 27130733, 2016). "The remaining genes found to be negatively regulated by MYCN and TFAP4, appear to be largely uncharacterised in cancer and their functions in neuroblastoma require investigation." (PMID 27448979, 2016). "n-Myc (MYCN) is oncogenic transcription factor, which can directly upregulate ODC expression in neuroblastomas." (PMID 27433286, 2016).
neuroblastoma (continued). "To investigate the effectiveness of PF-06463922 in vivo we orthotopically injected human neuroblastoma cells (CLB-BAR, amplified MYCN/ALK, ALKΔexon 4-11) into the adrenal glands of BalbC/nude mice, prior to treatment with either crizotinib or PF-06463922." (PMID 27483357, 2016). "MYCN, another MYC isoform, is amplified in pediatric neuroblastoma and has been shown to regulate metabolic pathways in a similar way as MYC." (PMID 27880818, 2016). "Microarray analysis identified genes regulated by both MYCN and TFAP4 in neuroblastoma cells, including Phosphoribosyl-pyrophosphate synthetase-2 (PRPS2) and Syndecan-1 (SDC1), which are involved in cancer cell proliferation and metastasis." (PMID 27448979, 2016). "Here we provide several lines of evidence demonstrating PRMT1 as a novel regulator of MYCN and implicating PRMT1 as a potential therapeutic target in neuroblastoma pathogenesis." (PMID 27571165, 2016). "We next mined Wnt gene related data from our previously performed RNAi screen targeting the druggable genome in the neuroblastoma cell line SY5Y-MYCN, in which MYCN overexpression can be induced." (PMID 27531891, 2016). "Taken together, these data indicate that both PRPS2 and SDC1 are co-operatively regulated by both MYCN and TFAP4 in neuroblastoma cells." (PMID 27448979, 2016). "Here we identified GRHL1 as a transcriptional activator of the CD9 gene and showed that MYCN and HDAC5 transcriptionally repress CD9 in neuroblastoma." (PMID 27572323, 2016). "Collectively these findings suggest that concomitant inhibition of both MYCN and LSD1 reduces neuroblastoma cell viability through activation of the apoptotic process." (PMID 26062444, 2015). "As MYCN was essential for proliferation of these cells, the SH-SY5Y neuroblastoma model provides a physiological relevant model to study the functional interactions between TRPM7 and MYCN in cell proliferation." (PMID 25797249, 2015). "Schulte and colleagues have identified in vitro seven miRNAs (miR-92, miR-106a, let-7b, miR-17-5p, miR-93, miR-99 and miR-221) induced by MYCN, a member of the MYC family, and positively correlating with MYCN-amplification in neuroblastoma." (PMID 26694467, 2015). "We also demonstrates that the development of TICs is due to an increased expression of MYCN gene and that in neuroblastoma exists an inverse relationship between LMNA and MYCN expression." (PMID 26439802, 2015). "Loss of these properties in the small molecule JMJD1A inhibitor DMOG treated NB cell lines, suggests that MYCN target genes could be used as potential therapeutic targets in the treatment of neuroblastoma." (PMID 26087192, 2015). "To evaluate the impact of N-Myc on oxidative glutamine metabolism, we analyzed glutamine consumption and ammonia production in SHEP MYCN-ER, a MYCN single-copy neuroblastoma cell line bearing a 4-hydroxytamoxifen (4-OHT) activating MYCN transgene." (PMID 26528759, 2015). "In neuroblastoma tumor models, I-BET 762 can trigger apoptosis through BET inhibition of N-Myc-driven pathways, including the direct suppression of Bcl-2 and MYCN." (PMID 25849938, 2015). "To directly evaluate its roles in this event, we depleted N-Myc expression by two specific shRNAs in Kelly and BE-2C, two MYCN-amplified neuroblastoma cell lines exclusively expressing high levels of N-Myc protein." (PMID 26528759, 2015). "Our previous results in neuroblastoma cell lines suggested that MLN8237 blocks the interaction between Aurora A and MYCN, exposing MYCN to proteasomal degradation." (PMID 25785590, 2015). "Similar to neuroblastoma, SCLC has an etiological link to Myc-family of oncogenes including MYC (c-Myc), MYCN (N-Myc) and MYCL1 (L-Myc)." (PMID 26380220, 2015). "High levels of TrkA and TrkC is expressed in biologically favourable neuroblastoma while high levels of TrkB and its ligand BDNF is expressed in biologically unfavourable aggressive neuroblastoma with MYCN amplification." (PMID 26010602, 2015).
neuroblastoma (continued). "Using neuroblastoma cells that are made to express high levels of MYCN, experiments by Penner and colleagues suggest that TRPM7 expression is required for MYCN-enhanced proliferation of neuroblastoma cells." (PMID 25797249, 2015). "We showed here that PKMYT1 is required to stabilize the MYCN protein in neuroblastoma cells by reducing T58 phosphorylation by the cdk1/gsk3 kinases, explaining the synthetic lethal effect of PKMYT1 inactivation in MYCN-amplified cells." (PMID 25477524, 2015). "To validate this MYCN-driven neuroblastoma progression model, we evaluated the expression of 50 known MYC(N)-regulated miRNAs, summarized in a MYCN signature score." (PMID 25294817, 2015). "Therefore, our findings reveal a number of novel points of functional cross-talk between MYCN and the MAPK signalling pathway, suggesting that ERK inhibition could be a viable target not only for NF1 mutated, but neuroblastoma in general including MNA neuroblastoma." (PMID 26673823, 2015). "Human Kelly MYCN-amplified neuroblastoma cells were treated with increasing concentrations of PIK-75 or PW-12 and blotted for markers of PI3K activity and MYCN protein." (PMID 26029667, 2015). "As previously reported, upregulation of cdks is common in aggressive neuroblastoma, but only CCNB1/cdk1 were predictive of outcome both in the entire cohort as well as in the MYCN normal group when the Cyclin/cdk pairs were considered." (PMID 26029996, 2015). "OSU-03012, a 3-phosphoinositide-dependent kinase-1 (PDK1) inhibitor, destabilizes MYCN and MYC proteins in neuroblastoma cells." (PMID 25017515, 2014). "The luciferase reporter construct with the full length MYCN 3′UTR was generated and subsequently integrated in the CHP134 neuroblastoma cell line." (PMID 24515800, 2014). "In contrast to MYCN transgenic mice, neuroblastomas in MYCN/NCYM double transgenic mice were frequently accompanied by distant metastases, behavior reminiscent of human neuroblastomas with MYCN amplification." (PMID 24391509, 2014). "Although the presence of homogenous amplification of the MYCN oncogene is central to the risk stratification systems in virtually all cooperative clinical trial groups, it is important to emphasize that the majority of aggressively behaving neuroblastomas do not show amplification of this oncogene." (PMID 25161957, 2014). "v-myc avian myelocytomatosis viral oncogene neuroblastoma derived homolog (MYCN) or anaplastic lymphoma receptor kinase (ALK), amplification and other genetic factors decide the aggressiveness and recurrence nature of neuroblastoma." (PMID 25148252, 2014). "MYCN is amplified in cancers such as neuroblastoma (NB), medulloblastoma, lung cancer and glioma." (PMID 24859015, 2014). "The number of apoptotic tumor cells was significantly decreased in the primary tumors of MYCN/NCYM double transgenic mice, suggesting that NCYM promotes the survival of neuroblastoma cells in vivo." (PMID 24391509, 2014). "The neuroblastoma-amplified gene (NAG), alternatively called neuroblastoma-amplified sequence (NBAS), was first identified as a gene co-amplified with the MYCN gene in neuroblastoma." (PMID 25364732, 2014). "A possible link between MYC/MYCN destabilization and UPR in S(+)-ibuprofen treated neuroblastoma cells is also discussed." (PMID 24173829, 2014).
neuroblastoma (continued). "Further studies are necessary to explore the possible interaction between MYCN/MYC up regulation and SMURF2 copy number gains in neuroblastoma in relation to suppression of TGFβ signaling." (PMID 23308108, 2013). "In a subsequent neuroblastoma study, CIMP was proven to be a predictor of progression-free survival superior to MYCN amplification, stage and age at diagnosis." (PMID 23717404, 2013). "A better comprehension of these mechanisms and the identification of those nuclear proteins that engage MYCN during oncogenesis may highlight new druggable molecular targets that will be helpful to look for new anticancer drugs specifically focalized on defeating neuroblastoma." (PMID 23482921, 2013). "Our observations of potent BET inhibitor activity in neuroblastoma are consistent with a recent report using a different BET inhibitor, JQ1, which was similarly shown to inhibit expression of MYCN and downstream N-Myc target genes." (PMID 24009722, 2013). "More recently, the discrepancy between genotype (MYCN amplification detected by FISH) and phenotype (MYCN protein levels) has been described in cases of MYCN amplified neuroblastomas with better prognosis." (PMID 24396620, 2013). "Moreover, miRNAs contribute to retinoic acid induced differentiation in neuroblastoma: miR-10a and miR-10b play a key role in neural cell differentiation through direct targeting of nuclear receptor corepressor 2 and concomitant downregulation of MYCN, a potent oncoprotein in neuroblastoma." (PMID 23503168, 2013). "Instead, our data indicate that inhibition of MYCN by a BET inhibitor is more ubiquitous and potent than MYC in neuroblastoma." (PMID 24009722, 2013). "In neuroblastoma AURKA has been found to be expressed at high levels in MYCN amplified tumors and required for the growth of MYCN amplified cells." (PMID 23226679, 2012). "We have demonstrated that neuroblastoma tumor cell NET protein expression correlates with clinical MIBG avidity and also with tumor MYCN status." (PMID 23050139, 2012). "In neuroblastoma, direct regulation of ATP-binding cassette (ABC) transporters by MYCN implicates MYCN as a mediator of drug-resistance in neuroblastoma." (PMID 22662276, 2012). "We further demonstrate that PTPRD has a tumor suppressor function in neuroblastoma through dephosphorylating and destabilizing AURKA, leading to a downstream decrease of MYCN protein." (PMID 22305495, 2012). "We have previously reported that B-Myb is essentially required for transcription of the MYCN amplicon and have also shown that B-MYB and MYCN are engaged in a feed forward loop promoting the survival/proliferation of neuroblastoma cells." (PMID 22619121, 2012). "Studies currently in progress involving cross breeding between MYCN transgenic mice and Abcc4 gene knockout mice will further assess the biological impact of MRP4 in neuroblastoma development, progression, and treatment response." (PMID 23267433, 2012). "PTPRD has a tumor suppressor function in neuroblastoma through AURKA dephosphorylation and destabilization and a downstream destabilization of MYCN protein, representing a novel mechanism for the function of PTPRD in neuroblastoma." (PMID 22305495, 2012).
neuroblastoma (continued). "In neuroblastoma tumors, SKP2 expression has been shown to tightly correlate with E2F1 expression, and both genes are expressed at significantly higher levels in MYCN amplified tumors." (PMID 23226679, 2012). "This is in agreement with recent demonstrations that high MYC-pathway activity is associated with poor outcome of the disease in neuroblastoma patients, irrespective of whether it was caused by MYCN-amplification, by increased c-MYC level or by any other cause." (PMID 22132187, 2011). "To verify the correlation between MYCN and B-MYB at the protein level, we carried out western blot analysis of B-MYB and MYCN expression in MYCN amplified and non amplified neuroblastoma cell lines." (PMID 21304178, 2010). "We initially observed that MYCN and B-MYB are co-expressed in neuroblastoma patients with aggressive or fatal disease." (PMID 21304178, 2010). "MYCN, a basic helix-loop-helix transcription factor that belongs to the MYC family, was initially identified as a gene amplified in neuroblastoma, the most frequent paediatric extra-cranial solid tumour." (PMID 20017904, 2009). "mRNA expression levels of MYCN, ΔMYCN and MYCNOS were measured in 16 human neuroblastoma samples by QPCR relative to three reference genes: GUSB, TFRC and RNFIII." (PMID 19615087, 2009). "In this study, we analyzed MYCN and c-MYC activity as reflected by the expression levels of a core set of direct MYCN/c-MYC targets in neuroblastoma subtypes." (PMID 18851746, 2008). "Almost all 140 target gene promoters showed binding of MYCN and/or c-MYC in the six analyzed neuroblastoma cell lines as measured by ChIP-chip." (PMID 18851746, 2008). "We defined a core set of direct MYCN/c-MYC target genes by applying gene expression profiling and chromatin immunoprecipitation (ChIP, ChIP-chip) in neuroblastoma cells that allow conditional regulation of MYCN and c-MYC." (PMID 18851746, 2008). "ChIP-chip experiments were performed with a monoclonal antibody against human MYCN and a polyclonal antibody against human c-MYC for each of the neuroblastoma cell lines." (PMID 18851746, 2008). "Whenever MYCN and c-MYC are co-expressed in neuroblastoma cell lines, c-MYC expression predominates." (PMID 18851746, 2008). "We also asked whether direct MYCN/c-MYC target genes as defined by our analyses are represented in previously published gene expression-based classifiers that distinguish low-risk from high-risk neuroblastomas independent of other risk markers." (PMID 18851746, 2008). "We further investigated the expression of these direct MYCN/c-MYC target genes in relation to MYCN and c-MYC expression in different clinical neuroblastoma subtypes." (PMID 18851746, 2008). "To identify MYCN/c-MYC-regulated genes in neuroblastoma cells, we employed the experimental system SH-EPMYCN, which stably expresses a tetracycline-regulated MYCN transgene." (PMID 18851746, 2008). "We used five neuroblastoma cell lines that either preferentially express high levels of MYCN (SH-EPMYCN, IMR5/75 (approximately 75 copies of MYCN), and Kelly (approximately 100-120 copies of MYCN)) or c-MYC (SJ-NB12 and SY5Y)." (PMID 18851746, 2008). "MYCN is a member of the MYC family of oncogenes and is over-expressed preferentially in tumours of neuroectodermal origin, particularly neuroblastoma." (PMID 18789162, 2008). "Correlation between MYCN overexpression and upregulation of NME1 expression has been reported both in NBTs and neuroblastoma cell lines." (PMID 18700951, 2008). "The nonrandom association of 3p LOH with 11q LOH in neuroblastoma likely signifies losses of tumor suppressor genes on these chromosome arms and may represent a synergistic alternative oncogenic pathway in high-risk tumors lacking MYCN amplification." (PMID 17327916, 2007).